MAPT-AS1 (MAPT antisense RNA 1)
Synonyms: MAPT-AS
Gene: Long non-coding RNA gene on chromosome 17 (45,799,390 to 45,895,704, reverse strand). Ensembl gene ENSG00000264589.
Diseases named in the same sentence as MAPT-AS1 in open-access papers:
MAPT-AS1 is named in the same sentence as 3 diseases in open-access papers, as found by Europe PMC text mining. Sharing a sentence is not in itself a finding about the gene and the disease. The quoted sentences say what the papers report.
breast carcinoma (2 papers, 2022 to 2024). "It has further been reported that, together with CYTOR, and MAPTAS1, MIR4458HG was an independent prognostic factor in breast cancer patients (10.21203/rs.2.24062/v1, preprint), with high expression associated with lower hazard ratios." (PMID 38253617, 2024).
neuroblastoma (1 paper, 2025). Neuroblastoma (NB) is the most common solid, extracranial childhood tumor. "We screened a total of 42 ASOs tiling the mature reference MAPT-AS1 transcript in a human neuroblastoma cell line (SK-N-MC) previously reported to express MAPT-AS1 and identified several candidate lead ASOs that reduced MAPT-AS1 levels by at least 50%." (PMID 39761259, 2025).
schizophrenia (1 paper, 2025). A major psychotic disorder characterized by abnormalities in the perception or expression of reality. "Within the fetal analysis, genes located in chr17q21.31, such as MAPT-AS1, KANSL1, LINC02210, MAPK8P1P2, and RP11-259G18.1, were regulated by eQTLs that have known associations with cognition, schizophrenia, and alcohol consumption traits." (PMID 40000109, 2025).